BCL2 (BCL2 apoptosis regulator)
Diseases named in the same sentence as BCL2 in open-access papers (continued):
Sharing a sentence is not in itself a finding about the gene and the disease.
tumor (continued). "The results of Western blot were consistent with the results of mRNA level, which fully demonstrated that CGOML can markedly reduce the tumor size by inducing in vivo apoptosis of MCF-7 cells by downregulating Bcl-2, and survivin expression and upregulating BAX expression." (PMID 27248325, 2016). "Taken together, the studies support the possibility of therapeutic potential in using Bcl-2 inhibitors in susceptible tumors with other oncogenic driver mutations and/or in combination with MEK, ERK, or RAF inhibitors that can specifically target tumor cells." (PMID 28025559, 2016). "Thus, the synergistic actions of PTX and Bcl-2 siRNA on cancer cells and in tumor model resulted in the significantly improved anti-cancer effect of PTX42." (PMID 27786239, 2016). "We investigated the immunolabeling of phosphorylated histone H3 (pHH3), cyclin D1, active caspase-3, and bcl-2 in thirteen cases each of metastatic PTC, follicular variant of PTC (FVPTC), papillary microcarcinoma (PMC) and well differentiated tumor of uncertain malignant potential (WDT-UMP)." (PMID 26863116, 2016). "We have shown that the levels of IKKβ and BCL2 tend to be higher in tumor cell lines that have high basal NRF2 activity, suggesting that mutant or low/absent levels of KEAP1 may contribute to elevated IKKβ and BCL2 levels." (PMID 26301506, 2015). "The anti proliferation effect from Bcl-2 inhibits tumor progression on animals." (PMID 26494988, 2015). "Bcl2 is a proto-oncogene to inhibit cell apoptosis in the tumor development." (PMID 26556865, 2015). "In stem cells, a low Dox-induced increase in p-Akt and Bcl-2 may represent the same mechanism and biological role as in the tumor cells." (PMID 26645568, 2015). "In this experiment, we examined if endothelial cells expressing Bcl-2 could protect tumor cell from anoikis." (PMID 26509633, 2015). "These potent anti-tumor effects of SAHA could be due to its inhibitory effects on a number of key anti-apoptotic members of Bcl-2 and IAP family particularly survivin." (PMID 26000099, 2015). "Therefore, there is substantial interest in developing potential chemotherapeutic drugs that directly target pro-survival Bcl-2 proteins by mimicking the BH3 domain to unleash pro-apoptotic molecules in tumor cells." (PMID 26447615, 2015). "Additionally, the expression of Ki67 and Bcl-2 were significantly reduced in Oct4A KD xenografts and was consistent with overall reduced tumour size in Oct4A KD xenografts." (PMID 26260289, 2015). "Taken together, these studies indicate that short-time or low concentration exposure of Dox induces the upregulation of p-Akt and Bcl-2 in certain types of cells (e. g., tumor cell lines), but the biological importance of this response remains unknown." (PMID 26645568, 2015). "The fact that levels of the anti-apoptotic protein BCL-2 are only reduced on average by 40% suggests that either there are other as yet undiscovered targets of MM41, or possibly that this level of BCL-2 decrease is sufficient to drive tumour cells to apoptosis." (PMID 26077929, 2015). "The role of Bcl-2 in tumor progression and patient outcome therefore remains controversial." (PMID 25826088, 2015). "Immunohistochemically, tumor was bcl-2 and CD99+, SMA and S-100 -." (PMID 26449317, 2015). "The IHC staining of tumor tissues obtained from cisplatin-treated A549 xenografts supported the in vitro results by showing a higher number of Bcl-2 and Mcl-1 stained cells in tumors derived from sc cells than those from IL-6si cells (quantification is shown on the right)." (PMID 26313152, 2015).
tumor (continued). "Such patients may respond to chemotherapy used in combination with rituximab since our in vivo and in vitro studies revealed that the rituximab treatment inhibits the p38 MAPK/Bcl-2 pathway and sensitizes the resistant tumor cells to drug-induced apoptosis." (PMID 26475474, 2015). "PCNA and Bcl-2 are downregulated in INMAP-overexpressing tumour tissues." (PMID 25635878, 2015). "In fact, overexpression of Bcl-2 is a characteristic of drug-resistant tumor cells." (PMID 26170886, 2015). "In addition, miR-497 plays a tumor-suppressive role in human cancer cell lines by targeting BCL2, thereby inducing apoptosis." (PMID 26486082, 2015). "This difference between cancer cells and normal cells may be interpreted as an indication of a pre-activated Bcl-2-system in tumor cells." (PMID 26610208, 2015). "In tumor tissues examined by immunohistochemical staining, administration of AD-p53PTM-E7-11 resulted in remarkable up-regulation of caspase-3 and Bax, accompanied with decreased expression of Bcl-2 and cyclin A, B, D." (PMID 25732051, 2015). "With respect to p38 expression, 44 % of the p38+ tumor tissues were Bcl-2+ (p < 0.005)." (PMID 26475474, 2015). "Very recently, a group reported that microRNA 15a/16 (miR-15a/16), a tumor suppressor, could directly target wild HBx RNA sequence (nt1362-1383), thus consequently induced Bcl-2 expression." (PMID 25942596, 2015). "In addition, the 100-mg/kg/day S03-EA-treated tumor tissue revealed a downregulation of Bcl-2 and VEGF expression and an upregulation of Bax expression." (PMID 25624914, 2015). "Furthermore, the overexpression of CDX2 upregulated the expression of Bax and downregulated the expression levels of survivin, Bcl-2, cyclin D1, Skp2 and c-Myc in the tumor tissues." (PMID 25738600, 2015). "The activation of Bcl-2 has been shown to enhance tumor growth and inhibition of apoptosis." (PMID 25823945, 2015). "Also, pathological parameters negatively correlated with disease prognosis were identified, including tumor infiltration and involvement of regional lymph nodes, adjacent structures or organs, high Ki-67, and Bcl-2 expression." (PMID 26271948, 2015). "We further detected the expression of Bcl-2 and Bax in xenograft tumours by immunohistochemistry and found that miR-106b could upregulate the expression of Bcl-2, while it significantly downregulated the expression of Bax." (PMID 26238857, 2015). "Indeed, NF-κB expression has been widely observed in diverse tumor types, in response to hyperactivation of Akt, and protects cells against cell death through activation of genes such as Bcl-2 and Bcl-xL." (PMID 26063499, 2015). "We found that the mitochondria showed abnormal changes in tumor cells that may result from elevation of the Bax/Bcl-2 and Bak/Bcl-2 ratios, which were involved in modulating mitochondrial function." (PMID 25915649, 2015). "High expression of Bcl2 in various human cancers mediates the resistance of cancers to a wide range of chemotherapeutic drugs and γ-irradiation which act by inducing apoptosis in tumor cells." (PMID 26074734, 2015). "The potential mechanisms driving aberrant expression of Bcl-2 proteins in tumor cells are diverse and may include gene amplification, epigenetic changes, posttranslational modifications as well as overactivation of upstream transcription factors (e.g. NFκB." (PMID 25885284, 2015). "It has been demonstrated that high-LET heavy ions irradiation could overcome the radioresistance of anti-apoptotic Bcl-2 overexpressing tumor cells." (PMID 25794049, 2015).
tumor (continued). "BM-957 is another ABT-737 derivative (a diphenyl-pyrrole-carboxamide scaffold linked to the nitrobenzene sulfonamide half of ABT-737): it also binds to BCL-2 and BCL-XL with sub-nM affinity, induces caspase 3-dependent apoptosis in tumor cell lines and causes tumor regression in xenograft models." (PMID 25970783, 2015). "The data suggested that indeed S3I-201 could decrease p-STAT3 and its target gene Cyclin D1 and Bcl2 effectively in vivo, which indicate the decrease of tumor size of nude mice using S3I-201 is an on-target effect." (PMID 26556875, 2015). "Most importantly, we found a mechanism for the anticancer activity of DMAMCL in vitro: DMAMCL may target Bcl-2 signal pathway to attack tumor cells." (PMID 25658946, 2015). "Interestingly, U2932 tumor cells, despite the high Bcl-2 protein expression, displayed high sensitivity to I-BET762 treatment and the mitochondrial membrane integrity was completely lost after treatment." (PMID 26658189, 2015). "Therefore, the cancer therapy based on silencing the specific gene such as Bcl-2 for killing tumor cells becomes a new and potential application in tumor treatment." (PMID 25852425, 2015). "In the presented analysis, based on BCL-2 expression, we could stratify patients with triple negative tumours into two subgroups with different prognosis." (PMID 25005788, 2014). "Pretreatment mRNA levels of BCL-2 negatively correlated with maximal tumor regression." (PMID 24983357, 2014). "Preclinical studies have found that KLT may block the tumor cell cycle at the G2/M phase, and induce tumor cell apoptosis by up-regulating the expression of Fas/Apo-1 and down-regulating the expression of Bcl-2 and COX-2." (PMID 25005526, 2014). "Notably, all filter samples (both 8 μm and 10 μm) showed higher BCL2 methylation levels than the corresponding sediment samples, indicating a higher fraction of tumor cells." (PMID 24732047, 2014). "Furthermore, the combination of BCL-2 siRNA treatment with a low dose of doxorubicin enhanced the autophagic response, tumor growth inhibition, and cell death." (PMID 25317422, 2014). "Moreover, many papers pointed out that the ability of anticancer agents to induce apoptosis of tumor cells was correlated with the ability to decrease expression of Bcl-2." (PMID 24901249, 2014). "Interestingly, rapamycin-resistant tumours have previously been reported to express high levels of bcl-2." (PMID 24457069, 2014). "COX-2 and Bcl-2 overexpression in the CG group suggests that CG, particularly the intestinal type, may be a premalignant lesion that converts into a tumor in the presence of carcinogens." (PMID 24387269, 2014). "Also, we observed the down-regulation of anti-apoptotic proteins Bcl-2 in HepG2 tumor cells by Nova." (PMID 24467885, 2014). "In the present study, we have shown, to the best of our knowledge, for the first time, 100 % DFS for patients having tumours characterized by low topoisomerase IIα expression and high microvessel density and BCL-2 positivity (all assessed by immunohistochemistry)." (PMID 25005788, 2014). "Univariate analysis showed that Borrmann type, depth of invasion, lymph node status, and expression of bcl-2 were associated with overall recurrence, whereas age, gender, histological type, tumor location, and tumor size were not." (PMID 24555747, 2014). "Overexpression of miR-143-3p in most cancer cells stagnates the growth of tumours and cancer cells as it may act to reduce BCL2 mRNA thereby preventing tumour or cancer cell proliferation and promoting apoptosis." (PMID 25238588, 2014).
tumor (continued). "COX-2 and Bcl-2 overexpression in CG suggests that CG, particularly the intestinal type, may be a premalignant lesion that converts into a tumor in the presence of carcinogens." (PMID 24387269, 2014). "However, it remains to be seen in which tumour types the simultaneous inhibition of all expressed antiapoptotic BCL2-proteins is sufficient to induce cell death and inhibit tumour growth." (PMID 26556430, 2014). "Therefore, future personalised cancer treatment will include BCL2-inhibitors in those tumours that express addiction to BCL2-proteins." (PMID 26556430, 2014). "To determine whether clotrimazole affects the apoptosis of tumor cells in vivo, we further analyzed the apoptotic tumor cells and the expressions of Bcl-2 and Bax in xenograft tumors by Immunohistochemistry and western blot analysis, respectively." (PMID 24892421, 2014). "This may also suggest that both the formation and growth of tumor is a dynamic process, during which cancer cells undergo constant changes in the synthesis and function of many proteins, including Bcl-2." (PMID 24741635, 2014). "Inhibition of ERK-, JNK- or Akt-mediated Mcl-1 stability may confer Bcl-2 inhibitor better anti-tumor effect in HCC cells." (PMID 24779770, 2014). "Thus, upregulation of anti-apoptotic Bcl-2 proteins and/or down-regulation of pro-apoptotic proteins can confer resistance to apoptotic stimuli on tumor cells." (PMID 24901320, 2014). "Apart from the inhibition of survival signalling, BCL2-inhibitors could also be combined with other targeted agents that induce apoptosis in tumour cells." (PMID 26556430, 2014). "In addition, silencing of LGR5 inhibited cell proliferation, secondary tumor sphere formation and induced cell apoptosis, and G0/G1 phase arrest in vitro by modulating Bcl-2, Bcl-xL and Bax." (PMID 24789370, 2014). "Therefore, downregulation of BCL-2 protein can restore intrinsic apoptotic pathways and resensitize tumor cells to apoptosis." (PMID 25231749, 2014). "In univariate analysis, longer DFS was found for patients having tumours with BCL-2 positivity (P = 0.005), low grade (P = 0.001), ER (P = 0.017) and PgR (P = 0.045) positivity, CK5/6 negativity (P = 0.021), low TOPOIIα expression (P = 0.003) and high MVD (P = 0.000)." (PMID 25005788, 2014). "The increased number of tumor cells in “LP type” DLBCL compared to the NLPHL component may result from enhanced anti-apoptotic properties resulting from BCL2 expression." (PMID 24885870, 2014). "Particularly, it may be assumed that a greater down-regulation of miR-15a/16-1 induces a lower suppression of Bcl2 anti-apoptotic activity, and consequently a greater tumor growth." (PMID 25232701, 2014). "The finding that residual tumors at the completion of chemotherapy express increased levels of Bcl-2 compared with pretreatment specimens suggests that Bcl-2 expression might be one mechanism for tumor resistance." (PMID 24755677, 2014). "In this type of tumor, apoptosis may also be inhibited by increased expression levels of the BCL2 gene." (PMID 25295115, 2014). "Bcl-2 is an oncogene and also a direct participant in the tumor cell apoptosis pathway." (PMID 25084400, 2014). "Furthermore, miR-182 has been shown to suppress the anti-apoptotic gene, BCL2, and to reduce tumour cell growth in vivo." (PMID 25510783, 2014). "Recently, some pharmaceutical companies have developed several medications such as Novartis-LBH589, cIAP1, and cIAP2 which inhibit the Bcl-2 protein, thus promoting cell death (apoptosis) and tumor regression, prevent or delay tumor resistance, and prolong remission following gene therapy." (PMID 26056594, 2014).
tumor (continued). "Therefore, the simultaneous targeting of MCL1 and BCL-2/BCL-XL is required to increase the apoptotic cell death of tumor cells." (PMID 24523919, 2014). "Therefore, development of new, dual Bcl-2 and Bcl-xL inhibitors with improved potency and efficacy will provide an opportunity to effectively target tumor cells whose survival is protected by both Bcl-2 and Bcl-xL or by Bcl-xL alone." (PMID 24901320, 2014). "In fact, several studies showed that inhibition of Bcl-2 sensitizes tumor cells toward ionizing radiation, revealing that Bcl-2 and, possibly, other members of this protein family may serve as candidates for targeted approaches in the future." (PMID 24141602, 2014). "Similarly to the other members of the family, miR-181a directly targets the BCL2 oncogene, thus providing further evidence of its anti-tumor effect in B-CLL." (PMID 25232701, 2014). "However, the direct regulation of Bcl-2 by miR-181a has been confirmed by many investigations, mainly in tumor cells." (PMID 24683439, 2014). "Bcl-2 was the first identified antiapoptotic gene and is widely expressed by hematopoietic cells, epithelial cells, lymphocytes, nerve cells, and a wide variety of tumor cells." (PMID 25177684, 2014). "In conclusion, COX-2 and Bcl-2 overexpression in CG suggests that CG, particularly the intestinal type, may be a premalignant lesion that converts into a tumor in the presence of carcinogens." (PMID 24387269, 2014). "Furthermore, tumor cells exposed to reversible or irreversible EGFR TKIs display early resistance dependent on MET-independent activation of BCL-2/BCL-XL survival signaling." (PMID 25364578, 2014). "It is thought that this induced resistance in a wide variety of tumor cells occurs via induction of NF-κB effector genes, including Bcl-2, Bcl-xL, survivin, XIAP, c-IAP1 and c-IAP2 that are known to mediate protective responses to chemotherapeutic agents and radiation." (PMID 23437404, 2013). "Furthermore, HL-60 cells were xenografted into nude mice and treated by crocin, the tumor weight and size were calculated, and the expression of Bcl-2 and Bax in xenografts was detected by immunohistochemical staining." (PMID 23573146, 2013). "To investigate whether the regression of tumor growth by crocin is due to the induction of apoptosis in vivo, we performed immunohistochemistry analysis of Bcl-2 and Bax expression in xenograft." (PMID 23573146, 2013). "The antiapoptotic proteins Bcl-2 and Bcl-XL play a transcendent role in chemoresistance in tumor cells; therefore, these proteins could be regulated by the NF-κB transcription factor." (PMID 23445492, 2013). "This association of BCL2 and favorable outcome may relate to the fact that BCL2 is an estrogen-regulated gene, thus indicative of an intact pathway driving tumor growth and thereby sensitivity to Tamoxifen." (PMID 23342080, 2013). "The difference in the percentages in comparison with sporadic tumours may be due to differences in scoring criteria, but may also be due to actual decrease in bcl-2 expression in FAP lesions." (PMID 23476634, 2013). "In addition to its inhibitory role on cell proliferation, Smad3 can exert a tumor suppression function in hepatic cells by downregulating the antiapoptotic protein BCL2, which results in TGF-β-mediated apoptosis." (PMID 24047375, 2013). "These important observations not only support previous findings that Cyclin D1 and Bcl-2 are target genes silenced by miR-195 but also demonstrate that the expression of miR-195 is potentially a more accurate prognostic tumor marker than Cyclin D1 or Bcl-2 levels alone in TSCC patients." (PMID 23451060, 2013). "Bcl-2 down-regulation has been shown to be important in the induction of tumor cell death." (PMID 23675407, 2013). "It is believed that prevailing a blockade induced by Bcl2 or Bcl-xl could restore normal cellular homeostasis, reverse the drug-resistant phenotype, and restore tumor cell sensitivity to conventional chemotherapeutics." (PMID 23956872, 2013).